TAS2R10 (taste 2 receptor member 10)
Description:
Gustducin-coupled strychnine receptor implicated in the perception of bitter compounds in the oral cavity and the gastrointestinal tract. Signals through PLCB2 and the calcium-regulated cation channel TRPM5.
Synonyms: T2R10; TRB2
Tractability: Antibody: its Gene Ontology location is reachable by antibodies, with high confidence; UniProt predicts a signal peptide or a membrane-spanning region; the Human Protein Atlas places it where antibodies can reach. PROTAC: a small molecule that binds it is known.
Target class: Membrane receptor; Taste receptor (taste family GPCR); Taste family G protein-coupled receptor
Gene: Protein-coding gene on chromosome 12 (10,825,219 to 10,826,358, reverse strand). Ensembl gene ENSG00000121318.
Subcellular location: Membrane
Subcellular location (Human Protein Atlas): Plasma membrane; Vesicles; Actin filaments
Pathways (Reactome):
Signal Transduction: Class C/3 (Metabotropic glutamate/pheromone receptors); G alpha (i) signalling events
Sensory Perception: Sensory perception of sweet, bitter, and umami (glutamate) taste
Gene Ontology:
Molecular function: bitter taste receptor activity; protein binding; taste receptor activity; G protein-coupled receptor activity
Biological process: detection of chemical stimulus involved in sensory perception of bitter taste; G protein-coupled receptor signaling pathway; sensory perception of taste
Cellular component: membrane; plasma membrane
Genetic constraint (gnomAD): Loss-of-function variants: 0 observed, 0.0866 expected, observed/expected ratio (o/e) 0, 90% interval 0 to 1.89. That is too few expected variants to judge how well the gene tolerates losing a copy. Missense variants: 379 observed, 376.29 expected, observed/expected ratio (o/e) 1.01, 90% interval 0.93 to 1.1. Synonymous variants: 141 observed, 133.05 expected, observed/expected ratio (o/e) 1.06, 90% interval 0.92 to 1.22.
Homologues: Orthologues: chimpanzee TAS2R10 (98% identical), macaque TAS2R10 (91% identical), dog TAS2R10 (74% identical), pig TAS2R10 (68% identical), rabbit TAS2R10 (63% identical), rat Tas2r107 (58% identical), mouse Tas2r114 (57% identical), mouse Tas2r106 (57% identical), mouse Tas2r107 (57% identical), rat Tas2r114 (55% identical), rat Tas2r105 (55% identical), mouse Tas2r104 (54% identical), and 3 more. Paralogues in human: TAS2R9 (40% identical), TAS2R7 (39% identical), TAS2R3 (39% identical), TAS2R14 (37% identical), TAS2R8 (36% identical), TAS2R42 (36% identical), TAS2R31 (36% identical), TAS2R30 (36% identical), TAS2R43 (36% identical), TAS2R46 (35% identical), TAS2R13 (35% identical), TAS2R19 (34% identical), and 11 more.
Diseases named in the same sentence as TAS2R10 in open-access papers:
TAS2R10 is named in the same sentence as 15 diseases in open-access papers, as found by Europe PMC text mining. Sharing a sentence is not in itself a finding about the gene and the disease. The quoted sentences say what the papers report.
neuroblastoma (5 papers, 2017 to 2024). Neuroblastoma (NB) is the most common solid, extracranial childhood tumor. "Our results are also in agreement with the previously reported role of TAS2R8 and TAS2R10 in abrogating migration of neuroblastoma cells." (PMID 32793492, 2020). "In neuroblastoma cells, TAS2R8 and TAS2R10 play an important role in inhibiting the self-renewal potential and the invasion ability of cancer cells." (PMID 32793492, 2020).
Obesity (2 papers, 2022 to 2025). Accumulation of substantial excess body fat. "Colocalization studies of TAS2R10, a broadly tuned TAS2R, showed that 8 of 54 TAS2R10 immunoreactive cells, stained positive for α-defensin 5 (15 %, n = 8 patients with obesity)." (PMID 34784295, 2022). "Paneth cells colocalize with TAS2R43 and TAS2R10+ cells, but goblet cells colocalize only with TAS2R43 in jejunal crypts of individuals with obesity." (PMID 34784295, 2022). "Activation of TAS2R10 by denatonium benzoate triggered Ca2+‐dependent release of antimicrobial peptides from Paneth cells, significantly suppressing E. coli growth—an effect amplified in obesity but absent in lean individuals." (PMID 40709685, 2025). "We analyzed approximately 842 immunopositive mucin 2 cells from 3 different individuals with obesity, but no clear colocalization with TAS2R10 could be identified." (PMID 34784295, 2022).
ovarian carcinoma (1 paper, 2023). A malignant neoplasm originating from the surface ovarian epithelium. "Our study revealed that high expression of TAS2R10, TAS2R3, and TAS2R50 is significantly associated with poor prognosis in ovarian cancer, as demonstrated by our analysis of clinical samples." (PMID 37799274, 2023).
pancreatic cancer (1 paper, 2021). "The activation of the bitter taste receptor TAS2R10 by caffeine in pancreatic cancer cell lines affected different signalling pathway molecules including the downregulation of ABCG2, a protein promoting multidrug resistance." (PMID 34885005, 2021).
pancreatic tumours (1 paper, 2021). "By means of immunohistochemical analysis, the related TAS2R10 protein was detectable in 79% of another cohort of pancreatic tumour tissue samples and the protein was located intracellularly as well as on the cell surface." (PMID 34885005, 2021). "There is significant evidence that cytotoxic effects of gemcitabine or 5-fluorouracil on pancreatic tumour cell lines are synergistically enhanced by the bitter-tasting food constituent caffeine through at least a partial activation of TAS2R10." (PMID 34885005, 2021).
cancer (4 papers, 2017 to 2024). A tumor composed of atypical neoplastic, often pleomorphic cells that invade other tissues. "The results of the present study demonstrate that TAS2R8 and TAS2R10 are endogenously expressed in NB cancer cells and they play noticeable roles in inhibiting the stemness, migration, and invasion of these cancer cells." (PMID 28467517, 2017). "In the present study, the role of TAS2R8 and TAS2R10 in the stemness of the NB cancer cells examined suggests their potential as chemotherapeutic targets, despite previously characterizations of TAS2Rs as elusive receptors with distinct signaling pathway and functions compared with other GPCRs." (PMID 28467517, 2017). "Cucurbitacin B, a triterpenoid known to act as an agonist for TAS2R10 and TAS2R14, shows promising anti-inflammatory and anti-cancer actions specific to the skin." (PMID 38248322, 2023).
tumor (3 papers, 2017 to 2023). "Here, stable expressions of TAS2R8 and TAS2R10 suppressed tumor incidence and tended to inhibit tumor growth." (PMID 28467517, 2017). "Effect of over-expressed TAS2R8 and TAS2R10 on tumor incidence, final tumor volume, and tumor weight." (PMID 28467517, 2017). "A significant increase in TAS2R10, TAS2R3, and TAS2R50 expression was observed in PNI-positive tumor tissue samples compared to PNI-negative." (PMID 37799274, 2023). "The upregulation of TAS2R8 and TAS2R10 counteracted gene expression of MMP-2 and P-selectin in tumour tissues, indicating an improved cell adhesion and therefore a reduced metastatic potential." (PMID 34885005, 2021).
infectious disease (1 paper, 2021). A disorder directly resulting from the presence and activity of a microbial, viral, or parasitic agent in humans. "It was reported that TAS2R10 is involved in the control of infectious diseases caused by bacteria, viruses, and parasites, suggesting that TAS2R10 is a key trigger of host defence pathways." (PMID 34831350, 2021).
TAS2R10 also shares sentences with these, for which no sentence is quoted: acute myeloid leukaemia (1 paper); asthma (1); breast carcinoma (1); glioma (1); nicotine addiction (1); pancreatic ductal adenocarcinoma (1); Parkinson disease (1).